IFNG (interferon gamma)
Description:
Type II interferon produced by immune cells such as T-cells and NK cells that plays crucial roles in antimicrobial, antiviral, and antitumor responses by activating effector immune cells and enhancing antigen presentation. Primarily signals through the JAK-STAT pathway after interaction with its receptor IFNGR1 to affect gene regulation. Upon IFNG binding, IFNGR1 intracellular domain opens out to allow association of downstream signaling components JAK2, JAK1 and STAT1, leading to STAT1 activation, nuclear translocation and transcription of IFNG-regulated genes. Many of the induced genes are transcription factors such as IRF1 that are able to further drive regulation of a next wave of transcription. Plays a role in class I antigen presentation pathway by inducing a replacement of catalytic proteasome subunits with immunoproteasome subunits. In turn, increases the quantity, quality, and repertoire of peptides for class I MHC loading. Increases the efficiency of peptide generation also by inducing the expression of activator PA28 that associates with the proteasome and alters its proteolytic cleavage preference. Up-regulates as well MHC II complexes on the cell surface by promoting expression of several key molecules such as cathepsins B/CTSB, H/CTSH, and L/CTSL. Participates in the regulation of hematopoietic stem cells during development and under homeostatic conditions by affecting their development, quiescence, and differentiation (By similarity).
Synonyms: IFG; IFI; IMD69
Tractability: Small molecule: a structure with a bound ligand is known; it has a binding pocket of medium quality. Antibody: an approved drug acts on it; its Gene Ontology location is reachable by antibodies, with high confidence; UniProt places it where antibodies can reach, with medium confidence; UniProt predicts a signal peptide or a membrane-spanning region. PROTAC: a small molecule that binds it is known.
Target class: Secreted protein
Gene: Protein-coding gene on chromosome 12 (68,154,768 to 68,159,740, reverse strand). Ensembl gene ENSG00000111537.
Subcellular location: Secreted
Pathways (Reactome):
Immune System: Gene and protein expression by JAK-STAT signaling after Interleukin-12 stimulation; IFNG signaling activates MAPKs; Interferon gamma signaling; Regulation of IFNG signaling
Developmental Biology: Differentiation of naive CD4+ T cells to T helper 1 cells (Th1 cells)
Gene expression (Transcription): RUNX1 and FOXP3 control the development of regulatory T lymphocytes (Tregs)
Gene Ontology:
Molecular function: cytokine activity; protein binding; type II interferon receptor binding
Biological process: apoptotic process; astrocyte activation; cell surface receptor signaling pathway via STAT; extrinsic apoptotic signaling pathway; Fc-gamma receptor signaling pathway involved in phagocytosis; immune response; macrophage activation involved in immune response; macrophage differentiation; microglial cell activation; negative regulation of DNA-templated transcription; negative regulation of gene expression; negative regulation of interleukin-17 production; negative regulation of smooth muscle cell proliferation; positive regulation of amyloid-beta formation; positive regulation of autophagy; positive regulation of chemokine production; positive regulation of cytokine production; positive regulation of epithelial cell migration; positive regulation of exosomal secretion; positive regulation of fructose 1,6-bisphosphate metabolic process; positive regulation of gene expression; positive regulation of inflammatory response; positive regulation of interleukin-12 production; positive regulation of interleukin-23 production; positive regulation of interleukin-6 production; and 34 more
Cellular component: extracellular region
Genetic constraint (gnomAD): Loss-of-function variants: 5 observed, 9.6 expected, observed/expected ratio (o/e) 0.52, 90% interval 0.27 to 1.1. That is too few expected variants to judge how well the gene tolerates losing a copy. Missense variants: 84 observed, 142.73 expected, observed/expected ratio (o/e) 0.59, 90% interval 0.49 to 0.71. Synonymous variants: 51 observed, 48.41 expected, observed/expected ratio (o/e) 1.05, 90% interval 0.84 to 1.33.
Homologues: Orthologues: chimpanzee IFNG (99% identical), macaque IFNG (94% identical), rabbit IFNG (66% identical), dog IFNG (66% identical), pig IFNG (60% identical), guinea pig IFNG (57% identical), mouse Ifng (38% identical), rat Ifng (31% identical), zebrafish ifng1 (23% identical), tropical clawed frog ifng (22% identical), zebrafish ifng1r (13% identical).
Diseases named in the same sentence as IFNG in open-access papers:
IFNG is named in the same sentence as 1,519 diseases in open-access papers, as found by Europe PMC text mining. Sharing a sentence is not in itself a finding about the gene and the disease. The quoted sentences say what the papers report.
COVID-19 (1,483 papers, 2020 to 2026). A disease caused by infection with severe acute respiratory syndrome coronavirus 2. "Inflammatory biomarkers associated with COVID-19 severity (IFNγ, and CD163) were associated with some symptoms and syndromes." (PMID 40449327, 2025). "Genetic polymorphisms in IFNG have been studied for their potential impact on the severity of COVID-19." (PMID 40919176, 2025). "Impaired production of IFNγ has been linked to COVID-19 severity, leading to prolonged inflammation and excessive production of pro-inflammatory cytokines." (PMID 40557167, 2025). "In a study of genes encoding cytokines, IFNG expression was significantly reduced in COVID-19 patients compared to that in controls." (PMID 40872774, 2025). "Among them were also the alleles with high expression of TNF -308 (A) and IFNG +874 (T) that correlated positively with COVID-19 mortality." (PMID 38675991, 2024). "High-titer IFNγ c-aAb were also more prominent specifically in men with non-COVID-19 viral infection, showcasing that different c-aAb are linked to different pathologies." (PMID 39606243, 2024). "This study indicated that IFNG gene expression in the peripheral blood mononuclear cells of patients with CRS associated with COVID-19 was significantly lower than in healthy controls." (PMID 38165854, 2024). "We observed reduced levels of lysophosphatidylcholines in severe COVID-19 patients, which is in line with previous studies, and strong associations with enhanced IFNγ." (PMID 39085233, 2024). "The *T allele of IFNG +874T/A (rs2430561) is associated with susceptibility to symptomatic COVID-19." (PMID 38675991, 2024). "Polymorphisms in the TNF and IFNG genes, particularly those related to the regulation of their expression, are natural candidates to play a role in the pathogenesis and evolution of COVID-19." (PMID 38675991, 2024). "Caspase-1 activation and a predominant IL-1/IL-6 signature associated with IFNγ-induced chemokines remain highly detectable in the BALF of steroid-resistant COVID-19-ARDS, arguing for new multi-targeted therapeutics in COVID-19-ARDS." (PMID 39882243, 2024). "COVID-19 mortality has been linked to a diminished ability to produce interferon-gamma (IFN-γ) and reduced early-stage activation of CD4+ and CD8+ T-cells." (PMID 39597537, 2024). "Although reports have shown that the serum IFNG level in patients with CRS associated with COVID-19 is significantly lower than that in healthy controls, the therapeutic effect of IFNG injection on patients with severe COVID-19 remains controversial." (PMID 38165854, 2024). "In this study, we investigated the associations of the TNF -308G/A and IFNG +874T/A polymorphisms with COVID-19." (PMID 38675991, 2024). "In humans, abundant CD4+CD154+ T cells are associated with severe COVID-19, particularly in T cells producing abundant proinflammatory cytokines, including interferon-γ (IFNγ), tumor necrosis factor, interleukin-2 (IL-2) and/or interleukin-21 (IL-21)." (PMID 37856551, 2023). "Factors associated with the levels of interferon-gamma after the administration of the Chinese inactivated COVID-19 vaccine." (PMID 36936962, 2023). "On the other hand, excessive production of pro-inflammatory cytokines, including IFNγ, has been found to be associated with COVID-19 severity." (PMID 36985262, 2023). "For instance, IL-6 and IL-8 have been associated with diagnostic and COVID-19 severity), while the expression of IFNγ was reduced in severely ill patients." (PMID 37569646, 2023). "A high IFNγ-producing T-cell activity is strongly associated with a low disease severity in acute and in convalescent COVID-19 patients." (PMID 36757971, 2023). "The literature and IPA’s Core Analysis of molecules associated with COVID-19 identified IFNG as the top upstream regulator upon downregulation in SARS-CoV-2 infection." (PMID 37686360, 2023).
COVID-19 (continued). "Although it needs to be confirmed by larger studies, this association suggests a role of in vitro IFNγ production as a possible biomarker for identifying COVID-19 patients with a higher grade of immunosuppression and mortality risk." (PMID 36016305, 2022). "In line with recent bioinformatic analysis of COVID-19 sequencing data we determined elevated expression of IFNγ -linked biomarkers, such as CXCL10, in both serum and nasopharyngeal swab material collected from patients with COVID-19." (PMID 35303909, 2022). "In non-COVID-19 immunocompromised patients, low in vitro interferon gamma (IFNγ) production correlates with infection risk and mortality." (PMID 36016305, 2022). "BALB/c mouse COVID-19 (mCOVID-19) is associated with an increased NK cell and interferon response and is ameliorated by IFNγ and TNF blockade." (PMID 35023830, 2022). "IFNγ was the cytokine showing the highest association with COVID-19 infection, and was therefore considered a significant risk factor for COVID-19 in our cohort (OR 169.2 (95% CI 5.5–5200.4); p = 0.003))." (PMID 36554094, 2022). "To characterize T cell responses, we performed interferon gamma (IFN-γ) enzyme-linked immune absorbent spot (ELISPOT) assays with the convalescent COVID-19 cohort and prepandemic controls." (PMID 33893169, 2021). "Several of these cytokines have been implicated as mediators of COVID-19; for instance, IL-6, IL-4, IL-10 and IFNγ." (PMID 34214142, 2021). "The propagation of systemic of systemic inflammation by CD8+ T cell derived cytokines (e.g., IFNγ) would presumably be bolstered by IL-10 mediated activation of tissue-resident mast cells, which are abundant in lung epithelial membranes and have been implicated in COVID-19-related inflammation." (PMID 34234779, 2021). "The magnitude of senescence led to a high surge of IL6, IL1b, IFNγ, C-reactive protein, and TNFα is reported in several epidemiological studies to lower airway and lung injury and risk for in COVID-19 elderly patients." (PMID 33815889, 2021). "While COVID-19 is characterized by an IFNγ deficiency or at least delayed responsiveness, NF-κB pathway activation seems to be central to the severe disease stage of COVID-19." (PMID 34578468, 2021). "On the other hand, asthma, a risk factor for adverse outcomes in COVID-19, is linked to IL-8, IL-5, IL-2, IFNg, eosinophils, and neutrophils." (PMID 32746922, 2020). "In fact, COVID-19-associated male infertility may involve a decrease in testosterone levels and spermatogenesis through shifts in cytokines such as IL-4, IL-6, IFNγ, and TNFα." (PMID 40507130, 2025). "Certain variants may influence the expression and activity of IFNG, thereby affecting individual susceptibility to severe outcomes in COVID-19." (PMID 40919176, 2025). "For this reason, the present study investigated the association of two single nucleotide polymorphisms (SNPs), TNF -308G/A (rs1800629) and IFNG +874T/A (rs2430561), with aspects of COVID-19 severity, becoming the first study to investigate the association of IFNG +874T/A with this infection." (PMID 38675991, 2024). "Similarly, IFNγ and IL-12 production abnormalities are linked to more severe COVID-19 outcomes as both cytokines are critical for effective antiviral response." (PMID 38612525, 2024). "In COVID-19 patients, the level of inflammatory cytokines is increased and plays a crucial role in the pathogenesis of the disease; among them, interferon-γ (IFNγ), TNFα, IL-1β and IL-6 are indicated as the key cytokines associated with the severity of COVID-19." (PMID 38542436, 2024). "In conclusion, this study revealed that IL-6R, TLR4, TLR2, and IFNG may be potential pathogenic genes in the CRS associated with COVID-19." (PMID 38165854, 2024). "The *T allele of IFNG +874T/A (rs2430561) is associated with susceptibility to COVID-19." (PMID 38675991, 2024).
COVID-19 (continued). "Hyperactivation of pro-inflammatory type 1 cytokines (e.g., tumor necrosis factor alpha [TNF-α] and interferon gamma [IFN-γ]) mirrors the inflammation of coronavirus disease 2019." (PMID 38727220, 2024). "However, the frequencies of the minor allele *T of the SNP rs2430561 (IFNG +874T/A) were 23.7 and 28.4% in previous studies, which are lower than in our COVID-19 sample (33.5%)." (PMID 38675991, 2024). "Our research group has demonstrated that hDPSCs can modulated the production of cytokines such as TNFα, IFNγ, IL-10 and IL-17A by peripheral blood mononuclear cells (PBMCs) obtained from Coronavirus disease 2019 (COVID-19) patients." (PMID 39450172, 2024). "Thus, genetic polymorphisms that affect the expression of genes encoding these cytokines (TNF and IFNG) are natural candidates for prognostic and predictive biomarkers in COVID-19." (PMID 38675991, 2024). "However, IFNG is actually associated with worsened outcomes in COVID-19 by contributing to inflammation and cytokine storm, possibly because IFNG can increase myeloid cell activation during toll-like receptor (TLR) signaling." (PMID 37361874, 2023). "For instance, some studies suggest that IFNγ-producing Th1 cells may play a positive role in COVID-19, and their higher activity may be associated with a milder disease course." (PMID 38179278, 2023). "Further, the severity of COVID-19 could also be due to delayed interferon-gamma response and is associated with a prolonged hyperinflammatory state as well as lower CD4+ and CD8+ cell numbers." (PMID 36839456, 2023). "IFNG is the topmost upstream regulator in the molecules associated with COVID-19." (PMID 37686360, 2023). "The authors concluded that individuals with AA have a slightly decreased risk of contracting COVID-19, potentially due to the protective effect of increased levels of interferon-gamma among the AA patients, which downregulates angiotensin-converting enzyme 2 in the body, the SARS-CoV receptor." (PMID 38186412, 2023). "The comparison of COVID-19 to controls at inclusion revealed the presence of a 14.4% difference in promoter-associated CpGs in genes that control immune-related pathways such as interferon-gamma and interferon-alpha responses." (PMID 36371196, 2022). "As severe COVID-19 is associated with exacerbated inflammatory responses, IFNγ and IL-17 expression in S-specific CD4 T-cells were evaluated by PBMC stimulation with Peptivators, and evaluation of cytokine expression by intracellular flow cytometry within T-cells." (PMID 36139625, 2022). "Our recent studies have suggested that cannabis extracts may inhibit the TNFα/IFNγ-induced inflammatory cytokine expression implicated in COVID-19." (PMID 35277472, 2022). "GSDME was also shown to be cleaved in PBMCs of healthy donors after treatment with a combination of TNF-α and IFNγ, two cytokines linked to COVID-19 severity, further indicating a potential role of GSDME as a backup mechanism for cell death during SARS-CoV-2 infection." (PMID 35244141, 2022). "Moreover, Interleukin 6 (IL-6) and IFNγ can reduce the incidence, severity, and risk of death from infections such as COVID-19." (PMID 36293182, 2022). "Poor IFNγ response, especially in the fall, might put the elderly at higher risk for severe COVID-19." (PMID 34434199, 2021). "In COVID-19, the loss of cytokine production (IL-2, IFNγ or TNFα) and antiviral activity (CD107a and Granzyme B) in both CD4+ and CD8+ T cells may be an important contributing factor to disease severity." (PMID 33575657, 2021). "IFNγ was the most prominent, which is amongst the most potent activators of the immune response in viral infection and the exuberant response was linked to unfavorable sepsis and COVID-19 outcomes." (PMID 34608231, 2021). "The COVID-19 cytokine profile of patients is closely associated with cytokine release, indicating macrophage activation, and an increase in the level of cytokines such as the TNFα, IL-6 and interferon-gamma (IFN-γ)." (PMID 33927728, 2021).